BNIP3 (BCL2 interacting protein 3)
Diseases named in the same sentence as BNIP3 in open-access papers (continued):
Sharing a sentence is not in itself a finding about the gene and the disease.
cancer (continued). "BNIP3, a BCL-2 family protein, is known to be transcriptionally regulated by HIF-1α and to be involved in cancer cell death in hypoxic conditions." (PMID 31078780, 2019). "For example, BNIP3 and NIX are highly expressed in breast, macrophage, endothelial and epithelial cancer cells compared to healthy cells from the same patient upon hypoxia induction." (PMID 30250843, 2018). "Other proteins linking mitophagy with the development of cancer are Parkin, BCL2/adenovirus E1B 19-kDa interacting protein 3 (BNIP3) and AMBRA1." (PMID 30344951, 2018). "Hypoxia-induced autophagy via BNIP3 and BNIP3L has been described as a stress-survival mechanism in mouse embryonic fibroblasts and various cancer cell lines to promote cancer progression." (PMID 29263786, 2017). "We found that Sabutoclax induced cancer-specific cell death in OSCC in a Mcl-1-dependent manner, which was attributed to both Bak-induced apoptosis and Bnip3-mediated mitophagy." (PMID 26009874, 2015). "For example, Bnip3 (BCL2 19 kDa-interacting protein 1), a pro-apoptotic factors of the Bcl-2-family, has been previously shown to be up-regulated in malignant tumors." (PMID 17118139, 2006). "In this study, we showed that increased BNIP3‐driven mitophagy in hypoxia‐exposed oral CSCs, mainly via activation of DRP1 (higher phosphorylation at Ser616), resulted in cancer cell growth, including increased cell proliferation, reprogrammed glycometabolism to OXPHOS, and EMT." (PMID 39945227, 2025). "It is interesting to note that BNIP3 signals for apoptosis or mitophagy (i.e., removal of damaged mitochondria through autophagy) depending upon its interaction with LC3 and ONC201 has been shown to kill cancer cells by targeting mitochondria." (PMID 40305155, 2025). "Additionally, hypoxic CAF-derived exosomes increase MMP-9 and IL-8 expression, enhancing cancer cell invasion via GPR64, with BNIP3 phosphorylation regulating the process." (PMID 40230452, 2025). "Additionally, autophagy, an intracellular degradation process, is activated in muscle-wasting conditions and is associated with increased expression of autophagy markers such as BNIP3 and LC3B in patients with cancer." (PMID 39727925, 2024). "On the contrary, knockdown of MAP3K5, LURAP1L, BNIP3 and HMOX1 enhanced cancer cell migration." (PMID 36899330, 2023). "Using transcripts per million reads normalization, BNIP3 expression was investigated in cancer samples and paired normal samples across different cancer types." (PMID 35912211, 2022). "In contrast to typical BH3-only proteins that bind to anti-apoptotic Bcl-2 family proteins via their BH3 domain, BNIP3 interacts with Bcl-2 and Bcl-XL specifically through its TM domain and N-terminus in cancer and non-cancer somatic cells." (PMID 36402748, 2022). "Further, BNIP3 has never been related to the effectiveness of chemotherapy response, whose molecular hallmarks remain a major goal in cancer research." (PMID 35459212, 2022). "Interestingly, the classical PINK1‐Parkin pathway and mitophagy mediated by BNIP3/Nix and FUNDC1 in response to hypoxia are also involved in glycolytic metabolism in cancer cells." (PMID 36200262, 2022). "Furthermore, BNIP3 and NIX are target genes of HIF-1α and their upregulation stimulates mitophagy under hypoxia and inhibits cancer progression in MMTV-PyMT model under hypoxia through activated HIF." (PMID 35205167, 2022). "Similarly, we observed overexpression of some critical cancer related and regulatory genes such as GADD34, DDIT4, BNIP3, BNIP3L, NOXA, and LC3B-II in response to AQ treatments confirming the role of AQ in regulating the autophagy and cancer regulatory genes." (PMID 36232751, 2022). "Recently, Sarah Riis and colleagues reported a conserved Akt/GSK-3β/Nrf2/BNIP3 pathway for regulating mitochondrial morphology and dynamics in mouse embryonic fibroblasts and cancer cells, which provides mechanistic clues for IGF-1-dependent BNIP3 transcription during differentiation." (PMID 35334906, 2022).
cancer (continued). "As previously reported, exogenous IGF-1 sustains cell viability in cancer cell lines by stimulating mitochondrial biogenesis and BCL2 protein-interacting protein 3-like- (BNIP3-) induced mitophagy, and IGF-1 can also augment mitochondrial function and neuronal metabolism via AMPK." (PMID 36062186, 2022). "With these questions in mind, we capitalized on cellular models of cancers resistant to CDDP to verify if it could be ascribed to changes in mitochondrial morphology, contacts with the ER and BNIP3-driven mitophagy." (PMID 35459212, 2022). "Indeed, the mitophagy proteins BNIP3L/NIX, BNIP3, and FUNDC1 were found upregulated in response to hypoxia in cancer." (PMID 35205167, 2022). "However, the role of BNIP3- and NIX-mediated mitophagy in cancer has to be carefully reevaluated, considering the fact that BNIP3 and NIX are proapoptotic BH3-only proteins." (PMID 32274386, 2020). "We recently reported that IGF-1 induces a transcriptional programme for mitochondrial biogenesis, while also inducing expression of the mitophagy receptor BCL2/adenovirus E1B 19 kDa protein-interacting protein 3 (BNIP3), suggesting that IGF-1 has a key mitochondria-protective role in cancer cells." (PMID 31936236, 2020). "Consistent with its role in cancer cell death, it is no surprise that BNIP3 expression was suppressed in several types of cancers." (PMID 31382612, 2019). "In cancer cells, nuclear p-STAT3-S705 can regulate the transcription of several autophagy-related genes such as BCL2 family members (e.g., BECN1, PIK3C3, CTSB, CTSL, PIK3R1, HIF1A, and BNIP3) and microRNAs with targets of autophagy modulators." (PMID 32565533, 2019). "On the other hand, BNIP3 is not expressed in other types of cancers such as the pancreatic, colorectal and gastric cancer even under hypoxic conditions." (PMID 30250843, 2018). "Moreover, BNIP3 is indicated to function as a pro-apoptotic BH3-only protein, which is related to the pathogenesis of many diseases, such as cancer and cardiovascular disease." (PMID 29018330, 2017). "BNIP3 depletion resulted in increased melatonin and sorafenib sensitivity and reduced cell viability, suggesting a cytoprotective role of hypoxia-related mitophagy in HCC cancer cells." (PMID 29207653, 2017). "Therefore, we examined the methylation of the BNIP3 and NIX promoters in 21 cancer cell lines using methylation-specific PCR (MSP)." (PMID 26727575, 2016). "Bcl-2 adenovirus E1B 19-kDa-interacting protein 3 (BNIP3), a member of the ‘BH3-only’ subfamily of pro-apoptotic Bcl-2 family proteins which induces cell death, has a key role in the pathogenesis of many diseases, such as cancer." (PMID 25891311, 2015). "Optimal supplementation of cancer cells in tissue culture with up to 1 mM ascorbate can suppress HIF-1α induction by a range of stimuli, and can reduce indicators of cancer aggression (VEGF-A, Glut-1, and BNIP3)." (PMID 28548062, 2014). "As DR5 protein was increased when BNIP3 expression was knocked down and it is a target for cancer therapy, we then sought to determine whether DR5 mRNA levels are regulated by nuclear BNIP3." (PMID 23579274, 2013). "Here we report, for the first time, that luteolin has a promotion on apoptosis and autophagy by the SGK1-FOXO3a-BNIP3 pathway in TNBC, which provides novel insights into the exploring of anti-cancer efficacy of luteolin and implies that SGK1 might provide a therapeutic target for TNBC." (PMID 37346292, 2023). "Notably, BNIP3 is a well-known HIF-1α target gene and its expression, together with the consequent mitophagy activation and inhibition of c-Myc-dependent mitochondrial biogenesis, promotes cancer progression and resistance to chemotherapy." (PMID 35459212, 2022). "In carcinoma, OA could increase ROS level, induce apoptosis, suppress angiogenesis and enhance mitochondrial dysfunction via inactivating sirtuin 1 (SIRT1)-forkhead box O3 (FOXO3)-BNIP3 axis." (PMID 36081929, 2022).
cancer (continued). "However, a study involving a cohort of patients with different stages of cancer did not confirm the negative prognostic role of nuclear BNIP3 in patients with NSCLC." (PMID 33207677, 2020). "BNIP3/NIX-mediated mitophagy contributes to the dox-resistance to CSCs in colorectal cancer and the silencing of BNIP3L both prevents mitophagy and increases the sensitivity to doxorubicin therapy, which suggests the importance of mitophagy in drug resistance for cancer therapy targeting CSCs." (PMID 32587855, 2020). "Thus, although mainly operating in concert, BNIP3 and NIX may affect mitochondrial degradation through independent mechanisms or in a cancer-subtype specific fashion." (PMID 31121959, 2019). "Our findings identify the critical role of BNIP3 in blockade of autophagosome-lysosome fusion mediated by BBM, and suggest that BBM could potentially be further developed as a novel autophagy inhibitor, which could enhance the effect of chemotherapy to cancer." (PMID 29445175, 2018). "However, HIF-1α and BNIP3 did not influence the cytotoxicity of Celastrol because the main mechanism by which Celastrol kills cancer cells is through stimulating ROS-mediated JNK activation and inducing apoptosis." (PMID 25383959, 2014). "BNIP3 silencing also maintained mitochondrial mass without disrupting oxidative balance, highlighting BNIP3’s central role in cancer cachexia and suggesting that targeting BNIP3 may help in supporting muscle health in cancer patients." (PMID 39766033, 2024). "Since BNIP3 and BNIP3L promote cell death, it is not surprising that upregulation of BNIP3 and BNIP3L were reported to block cancer stem cells in multi types of cancer." (PMID 26432836, 2015). "However, it is still not clear how BNIP3 expression, its induction by IGF-1, or the role of mitophagy in cancer cell metabolism is regulated or integrated with mitochondrial biogenesis and mitochondrial function." (PMID 31936236, 2020). "At gene level, Beclin-1, p-62, BNIP3, NIX/BNIP3L and TFEB mRNAs were not significantly modulated, while LC3B and PINK1 mRNA levels were increased and decreased, respectively, in cachectic cancer patients." (PMID 27459917, 2016).
infection (25 papers, 2010 to 2025). The state of being infected such as from the introduction of a foreign agent such as serum, vaccine, antigenic substance or organism. "Wild-type (WT) Ly49H + NK cells were transferred into Ly49H-deficient mice; upon infection, memory NK cells displayed levels of BNIP3 transcripts comparable to resting NK cells." (PMID 34396954, 2021). "Transcriptomic analyses and specific downregulation of protein expression with siRNAs suggested there is an association between the infection-specific over expression of BNIP3, as well as CTSE, and the autophagic activity of BMDM." (PMID 26226952, 2015). "Detailed analysis of the CHIKV viral cycle revealed that BNIP3 interferes with the early stages of infection." (PMID 38011286, 2023). "The mRNA expression of Bnip3 was significantly induced in bone marrow-derived macrophages (BMDMs) infected with Mtb 48 h post infection." (PMID 37649112, 2023). "We further confirmed that BNIP3 was induced by Mtb infection by evaluating BNIP3 expression in a multiplicity of infection (MOI)-dependent manner." (PMID 37649112, 2023). "Our results showed that the protein levels of BNIP3 were increased in Mtb-infected macrophages between 24 and 48 h post infection." (PMID 37649112, 2023). "Similar to the siRNA screen results at 17 hpi, knockdown of BNIP3 expression increased the number of infected cells by 2.0- and 1.9-fold upon infection at MOI 1 and 10, respectively, in comparison to the siScramble-transfected cells." (PMID 38011286, 2023). "We demonstrate that BNIP3 interferes with infection after virus membrane hemifusion but prior to abundant RNA replication." (PMID 38011286, 2023). "In response to mitochondrial damage due to infection or environmental stress, BNIP3 is expressed and localized to the mitochondria." (PMID 37649112, 2023). "Infection of primary OPCs with the N167 lentiviral vector resulted in almost complete inhibition of BNIP3 in OPCs." (PMID 36551300, 2022). "As expected, increased length of the viral genome, more than its unit length, due to insertion of foreign gene (BNiP3) did not affect the infectivity and replication competency of rMV-BNiP3 in subsequent infections." (PMID 30697531, 2018). "At day 3 in the TA and SOL muscles, infection triggered increases in the mRNA expression of several autophagy-related genes, including Lc3b, Gabarapl1, Bnip3, Parkin, Lamp2a, and Foxo1." (PMID 28659735, 2017). "The infection with Ad-BNIP3, Ad-NIX or both Ad-BNIP3 and Ad-NIX also resulted in a small decrease in MMP (M1: cont 11.6% and LacZ 11.5% vs BNIP3 20.9% and NIX 18.3%)." (PMID 22292033, 2012). "This shows that the role of BNIP3 in regulating CHIKV-LR infection could be involved in the replication of other CHIKV strains and other alphaviruses from the same antigenic complex." (PMID 38011286, 2023). "The mechanism was investigated by infection with lentivirus-mediated BNIP3 or E2F1 overexpression." (PMID 36284303, 2022). "ACAA2 binding abrogates BNIP3-mediated apoptosis; therefore, increased ACAA2 proteolysis may overall promote BNIP3-mediated apoptosis during infection." (PMID 32487743, 2020). "In our study, we detected greater levels of Foxo1 mRNA in the TA than in the DIA at day 3 post-infection, suggesting that Foxo1 may contribute to the up-regulation of Lc3b, Gabarapl1, and Bnip3 that is seen in the TA in response to infection." (PMID 28659735, 2017). "A significant upregulation of BNIP3 expression at the protein level was detected 24 h p.i., but not 1 h p.i., which suggests a putative inhibition of Bnip3 translation in the early infection phase." (PMID 26226952, 2015). "Moreover, in order to form NK cell memory, NK cells require Zbtb32 to undergo a proliferative burst and clonal expansion in response to infection, require BNIP3 and BNIP3L -dependent clearance of damaged mitochondria by autophagy, and require pro-apoptotic factor Bim for contraction." (PMID 32849653, 2020).
infection (continued). "Levels of CXADR, BNIP3, and SPARCL1 mRNA were measured during the persistent phase of infection with Ad5dl309 (56–77 days p.i.)and normalized to the housekeeping gene EIF1." (PMID 41497616, 2025). "We previously reported that expression of several cellular genes, including CXADR, BNIP3, SPARCL1, SLFN11, BBS9 and BNIP3, is significantly downregulated by epigenetic means during the persistent phase of infection of B cells." (PMID 41497616, 2025). "In agreement with previously reported results, infection reduced CXADR, BNIP3, and SPARCL1 expression to between 0.6% and 13% of the level detected in non-infected cells transduced with the empty vector." (PMID 41497616, 2025). "After two months of infection, the number of viral genomes was determined and the relative level of mRNA for CXADR, BNIP3, SPARCL1 and SLFN11 was measured in infected and mock-infected cells." (PMID 41497616, 2025). "Many genes in the autophagy and mitophagy signaling pathways, such as ULK2, BNIP3, WIPI1 and CTSB, presented significantly upregulated expression profiles following infection." (PMID 39650642, 2024). "The levels of BNIP3 and cleaved caspase significantly decreased in infected MFD-fed mice as compared to infected RD-fed mice during acute infection." (PMID 36676177, 2023). "To understand the PHI-driven changes in pulmonary gene expression we sequenced RNA from the lung tissue of vehicle, FG-4592 pre- or post- infection groups and observed an induction of 47 and 63 genes respectively, including HIF target genes such as Edn-1 and Bnip3." (PMID 36067210, 2022). "Bnip3 expression was only upregulated by a C. burnetii infection under normoxia, but not under hypoxia, while Bnip3l expression was not modulated by the infection at all." (PMID 35755850, 2022). "Nevertheless, we demonstrate that genetic deletion of the proposed SidF pro-apoptotic host cell target proteins, BCL-RAMBO, or BNIP3, also does not alter L. pneumophila replication, infection or host cell death kinetics." (PMID 28261564, 2017). "To address whether BNIP3 also controls the infection of other CHIKV strains, we examined the effect of BNIP3 depletion on the viral cycle of CHIKV-S27, the prototype strain originally isolated in 1953 and CHIKV-99659, a recently isolated Caribbean strain that belongs to the Asian Urban lineage." (PMID 38011286, 2023). "However, the infection rates of L. m.-infected BMDM significantly declined between 24 and 48 h p.i., which suggests there was a high autophagic activity accompanied by high BNIP3 and CTSE expression." (PMID 26226952, 2015). "Although NIX and BNIP3 were actually overexpressed in HCT116 cells by infection with the high dose of Ad-BNIP3 and Ad-NIX, we observed neither of the MMP reduction, the increased dead cells, nor the caspase-3 activation at both early (48 h after infection) and late phases (98 h after infection)." (PMID 22292033, 2012). "In all three muscles, infection induced increases in p62/SQSTM1 and BNIP3 protein levels, but exerted no influence on BECN1 or PI3KC3." (PMID 28659735, 2017).
cardiovascular disease (8 papers, 2007 to 2024). "Studies have shown that BNIP3 is a proapoptotic protein that is involved in the pathogenesis of cardiovascular disease through the regulation of mitochondrial functions." (PMID 26000071, 2015). "In the prevention and treatment of cardiovascular diseases, berberine mainly protects cardiac function by activating the PINK1-Parkin, HIF-1α/BNIP3 signaling pathways and promoting mitophagy." (PMID 36034426, 2022). "In this study, we identified that hypoxia upregulates BNIP3 gene expression in young, but not aged, CD34+ EPCs, indicating a potential role of BNIP3 in aging-related cardiovascular diseases." (PMID 29708992, 2018).
heart disease (4 papers, 2014 to 2020). "Furthermore, it has been reported that targeting BNIP3 in inflammation-related cardiac failure is a practical therapeutic strategy for heart disease." (PMID 33681183, 2020). "Our results show that cytosolic homo/heterodimerization of BNIP3 and interaction with mitochondria via mitochondrial BAX does not affect MIM potential and cell viability, unlike what was assumed to occur in cardiac disease." (PMID 28333095, 2017).
kidney (4 papers, 2012 to 2024). "Conversely, knockout of PTEN-induced kinase 1 (PINK1), parkin RBR E3 ubiquitin protein ligase (PARK2), or BCL2-interacting protein 3 (BNIP3) inhibited mitophagy in TECs, which aggravated kidney injury." (PMID 35501332, 2022). "Univariate analyses indicated a significant association between OS and primary tumor site, T stage, cervical lymph node metastasis, TNM stage, TGM2 expression and BNIP3 expression in laryngeal SCC." (PMID 22458929, 2012).
adenocarcinoma (3 papers, 2010 to 2022). A common cancer characterized by the presence of malignant glandular cells. "Interestingly, the expression level of BNIP3 will elevate in early-stage adenocarcinoma but decrease in metastasis progression." (PMID 36092153, 2022). "Among the novel methylated candidates identified, ID4, BNIP3, H2AFX, CACNA 1G, TGIF were more frequently methylated in squamous tumors, while HTLF and CACNA1A were commonly methylated in adenocarcinomas." (PMID 20849603, 2010). "Methylation rates for ID4, DCL1, BNIP3, H2AFX, CACNA1G and TIMP3 were significantly different between squamous and adenocarcinomas." (PMID 20849603, 2010). "Statistically significantly different methylation rates were observed for ID4-2 (p = 0.011), DCL1 (p = 0.019), BNIP3 (p = 0.003), H2AFX (p = 0.001), H2AFX-2 (p = 0.005), CACNA1G (p = 0.007) and TIMP3 (p = 0.021) when comparing squamous versus adenocarcinoma cases." (PMID 20849603, 2010).
metabolic disorders (3 papers, 2020 to 2025). "The absence of BNIP3 has been associated with chronic liver damage and metabolic disorders." (PMID 40588730, 2025).